STK25 (serine/threonine kinase 25)
Diseases named in the same sentence as STK25 in open-access papers (continued):
Sharing a sentence is not in itself a finding about the gene and the disease.
tumor (continued). "Our study identifies STK25 signaling as a critical driver of the initiation and progression of HCC by showing that genetic ablation of STK25 efficiently suppressed tumor development in 2 mouse models of hepatocarcinogenesis that closely recapitulated the nature of human HCC." (PMID 34624527, 2022). "Consistently, STK25 knockdown inhibited tumor growth in xenograft mouse model." (PMID 34986838, 2022). "STK25, as a member of the ROS family genes, is involved in lipid metabolism and tumor progression." (PMID 34795841, 2021). "Moreover, STK25 depletion combined with CAFs significantly enhanced CRC tumour growth in vivo." (PMID 42057436, 2026). "The effects of STK25 expression on CAF activity and CAF-mediated tumour progression were evaluated both in vitro and in vivo." (PMID 42057436, 2026). "The identification of ATG3, STK25, and DIRAS3 aligns with prior research implicating autophagy and tumor suppression mechanisms in CRC development." (PMID 41463182, 2025). "To confirm the difference in STK25 expression in the HCC tissues, we examined the tumor specimens and paracancerous tissues of 29 patients." (PMID 34986838, 2022). "Together, these data suggest that STK25 abrogation confers resistance to hepatocyte apoptosis induced by DEN or CDAA challenge, and suppresses HCC development through attenuated tumor cell proliferation and angiogenesis." (PMID 34624527, 2022). "STK25, as an important member of the GCK family subgroup III (GCK III), can regulate tumor progression by inhibiting the Warburg effect, inducing apoptosis, and negatively regulating oncogene transcription." (PMID 35756606, 2022). "Studies have shown that altering the activity or the expression level of STK25 and regulating cell proliferation/apoptosis/polarity by STK25/GM130/PDCD10 may provide new directions for tumor therapy." (PMID 35265128, 2022). "Furthermore, a recent study has shown that the complete absence of STK25 expression often results in a partial decrease in LATS activity and an increase in YAP/TAZ activity and finally promote tumor cell proliferation." (PMID 35756606, 2022). "Interestingly, in our study, the expression of AFP, YAP, GRP78, and EpCAM was attenuated in the livers from Stk25-/- mice, supporting the importance of STK25 not only in the development of HCC but also in tumor progression." (PMID 34624527, 2022).
metabolic disease (3 papers, 2017 to 2020). A congenital disorder (due to inherited enzyme abnormality) or acquired (due to failure of a metabolically important organ) disorder resulting from an abnormal metabolic process. "Thus, STK25 emerges as a key regulator governing susceptibility to lipotoxicity, and an inhibition of STK25 activity may prevent various complex metabolic diseases that are associated with ectopic lipid deposition in peripheral tissues, including kidney." (PMID 33170807, 2020). "Our findings highlight STK25 as a potential drug target for metabolic disease." (PMID 28442507, 2017).
STK25 also shares sentences with these, for which no sentence is quoted: Glucose intolerance (2 papers); non-alcoholic fatty liver disease (2); acute myeloid leukemia (1); adrenocortical carcinoma (1); behavioral disorders (1); brachydactyly (1); cerebral cavernous malformation (1); cervical cancer (1); diabetes (1); fibrosis (1); heart failure (1); lactic acidosis (1); lung adenocarcinoma (1); lupus (1); mesothelioma (1); microcephaly (1); neurodevelopmental disorder (1); Parkinson disease (1); prostate carcinoma (1); retinal disease (1); uveal melanoma (1).